FTH1 (ferritin heavy chain 1)
Diseases named in the same sentence as FTH1 in open-access papers (continued):
Sharing a sentence is not in itself a finding about the gene and the disease.
hepatitis B virus infection (1 paper, 2016). A viral infection caused by the hepatitis B virus. "The discrepancy of susceptibility of PDH to DHBV under different conditions was consistent with expression pattern of ferritin (FTH1) that was used as a predictor of host response to hepatitis B virus infection." (PMID 26900848, 2016). "In addition, expression of FTH1, a predictor of host response to hepatitis B virus infection in vivo was down-regulated in FBS-8d PDH but partially recovered in DMSO-8d PDH." (PMID 26900848, 2016).
hyperandrogenemia (1 paper, 2025). "This study identifies significant iron homeostasis disorders and ferroptosis in PCOS patients with hyperandrogenemia, which is mediated by androgen-induced reduction of ferritin heavy chain 1 (FTH1) protein levels in trophoblasts." (PMID 41400098, 2025).
hyperhomocysteinemia (1 paper, 2025). A serious metabolic condition caused by mutations in the MTHFR gene, medications, or nutritional deficiency. "The myocardial β-catenin and GPX4 in mice with hyperhomocysteinemia were markedly lower than the control group, whereas the expression of FTH1 remained unchanged." (PMID 40768425, 2025).
Infertility (1 paper, 2023). "The topological analysis of the WGCN of the testis transcriptional cell atlas highlighted important somatic genes in this network, including RPL39, RPL10, RPL13A, FTH1, RPS2, and RPL18A, which have been reported to be associated with infertility." (PMID 38012716, 2023).
influenza infections (1 paper, 2025). "Less is known about the influence of influenza infections on iron metabolism, where this study identified FTH1 and FTL as top DEPs, but it could be reflective of macrophage and/or IL-6 responses." (PMID 41346583, 2025).
iron (1 paper, 2025). "Nevertheless, analysis of transcriptional levels of FTH1 and FTL genes from public databases can also give clues for the correlation between macrophage activation and prognosis in iron overloaded AML patients." (PMID 40881683, 2025).
iron storage disorder (1 paper, 2021). "A recent study has shown that ferritin heavy chain 1 (FTH1) also plays an important role in ferroptosis and its abnormal expression leads to iron storage disorder and cell death by destroying the antioxidant defense function of cells." (PMID 34257815, 2021).
ischemia reperfusion injury (1 paper, 2025). Adverse functional, metabolic, or structural changes in ischemic tissues resulting from the restoration of blood flow to the tissue (reperfusion), including swelling; hemorrhage; necrosis; and damage from free radicals. "Silibinin targets FTH1, disrupts the NCOA4–FTH1 interaction, reduces ferroptosis-mediated cell death, and alleviates renal dysfunction, pathological damage, and inflammation in ischemia–reperfusion injury (IRI) AKI mice, effectively preventing ischemia–reperfusion-induced renal injury." (PMID 41425591, 2025).
keloid (1 paper, 2025). An irregularly shaped, elevated mark on the skin caused by deposits of excessive amounts of collagen during wound healing. "Immunofluorescence revealed the presence of RSL3 in these grafts, alongside a reduction in S100A4+FTH1+ fibroblast cells and PLIN1+α-SMA+ adipocyte cells in keloid grafts following RSL3 therapy, consistent with in vitro experiments." (PMID 40860189, 2025).
keratosis (1 paper, 2024). A skin disorder consisting of hypertrophy of the stratum corneum of the skin. "For expanded gene families, we found three genes were associated with skeletal development and/or bone density (HNRNPH1, LIN28A, and TARP) and two genes (FTH1 and KDSR) were related to keratosis." (PMID 39092175, 2024).
kidney stone (1 paper, 2024). "It is worthwhile emphasizing that the tool mitigated kidney damage in the stone model and minimized the degree of crystal deposition in kidney tissues by stably enhancing the expression intensity of the target gene FTH1, thereby significantly inhibiting the formation of kidney stones." (PMID 38714951, 2024). "Moreover, after stable performing of the single-vector AAV translation enhancement tool designed for FTH1, it could effectively attenuate the degree of ferroptosis in mouse kidney stone model and alleviate kidney damage." (PMID 38714951, 2024).
male infertility (1 paper, 2023). The inability of the male to effect fertilization of an ovum after a specified period of unprotected intercourse. "We also identified key somatic cell genes, including RPL39, RPL10, RPL13A, FTH1, RPS2, and RPL18A, which were highly influential in the weighted gene co-expression network of the testis transcriptional cell atlas and have been previously implicated in male infertility." (PMID 38012716, 2023).
metastatic cancer (1 paper, 2021). A carcinoma which has spread from the original site of growth to another anatomic site. "Increased FTH1 expression was also reported to render metastatic cancer more sensitive to chemotherapy." (PMID 34803511, 2021).
metastatic melanoma (1 paper, 2021). A melanoma that has spread from its primary site to another anatomic site. "However, FTH1 functions as a tumor suppressor in metastatic melanoma." (PMID 34853622, 2021).
myelodysplastic syndrome (1 paper, 2025). A clonal hematopoietic disorder characterized by dysplasia and ineffective hematopoiesis in one or more of the hematopoietic cell lines. "Single‐cell sequencing of lineage negative (Lin‐) cells from patients with myelodysplastic syndromes (MDS) revealed a reduction in ferritin heavy chain 1 (FTH1) levels, yet the significance of this decrease in FTH1 in the pathophysiology of MDS remains unclear." (PMID 39804099, 2025).
myopia (1 paper, 2021). "Furthermore, TMT analysis and PRM validation revealed that the expression of ferritin light chain (FTL, P02792) and ferritin heavy chain (FTH1, P02794) was negatively associated with myopia development, while the expression of serotransferrin (TF, P02787) was positively related to myopia status." (PMID 34660571, 2021). "Among the validation results, the abundance of TF was increased in the high myopia group, while FTL and FTH1 expression were both reduced in the high myopia group compared to the low myopia group." (PMID 34660571, 2021).
neural tumor (1 paper, 2019). "Using liposomes as a siRNA delivery system, we established FTH1 as a critical factor for survival in both GIC subtypes as well as a regulator of radioresistance and stemness in pro-neural tumor derived GICs." (PMID 31491006, 2019).
neurodegenerative eye diseases (1 paper, 2025). "Comparisons and correlation studies were used to verify the hypothesis of a Reelin, Aβ1-42, TAU and FTH1 marker expressions in this vitreoretinal disease, extending the knowledge on the pathological spectrum of neurodegenerative eye diseases." (PMID 40867631, 2025).
non-alcoholic fatty liver disease (1 paper, 2025). "Conversely, reduced YAP levels promote the binding of NCOA4 to FTH1, intensifying hepatocyte ferroptosis in non-alcoholic fatty liver disease." (PMID 40374601, 2025).
oral cancer (1 paper, 2024). "Treatment with TFP significantly upregulated the expression levels of pro-ferroptotic proteins, such as FTH1 and NCOA4, while downregulating the expression levels of proteins that reverse ferroptosis, such as SLC7A11, GPX4 and Nrf2, in oral cancer cells." (PMID 39664583, 2024).
oral candidiasis (1 paper, 2010). Infection of the mucosal lining of the mouth with the fungus Candida albicans. "The gene coding for Rim101 and three (in)direct target genes (FTH1, FRE4 (orf19.1844), CFL2,) proposed by the model were also up-regulated within expression data of patients suffering from oral candidiasis." (PMID 21050438, 2010).
osteoblastic osteosarcoma (1 paper, 2025). A conventional osteosarcoma characterized by the predominance of osteoid matrix. "In this study we evaluated the immunohistochemical expression of ferritinophagy-related proteins, namely Ferritin Heavy chain (FTH1) and NCOA4, and proliferating cell nuclear antigen (PCNA) in canine normal bone and canine osteoblastic osteosarcoma (COOS) samples." (PMID 40196812, 2025).
papillary thyroid carcinoma (1 paper, 2025). "APOE suppresses ferroptosis in papillary thyroid carcinoma (PTC) via the PI3K/AKT1 pathway, elevating GPX4/FTH1 expression while reducing Fe2+ accumulation." (PMID 41390817, 2025).
periodontitis (1 paper, 2024). An acute or chronic inflammatory process that affects the tissues that surround and support the teeth. "Moreover, we found specific proteins - drivers or suppressors - associated with ferroptosis (SNCA, FTH1, HSPB1, CD44, and GCLC), revealing the co-occurrence of this specific type of regulated cell death during the clinical progression of periodontitis." (PMID 38802345, 2024).
pneumonia (1 paper, 2023). An acute, acute and chronic, or chronic inflammation focally or diffusely affecting the lung parenchyma, caused by an infection in one or both of the lungs (by bacteria, viruses, fungi, or mycoplasma.). "Consistent with this notion, in the present study both FTH1 and FTL mRNA levels in peripheral blood mononuclear cells (PBMCs) were significantly higher in patients with pulmonary TB than in healthy controls and non-TB pneumonia patients." (PMID 37066876, 2023).
renal fibrosis (1 paper, 2024). A final common manifestation of a wide variety of chronic kidney diseases characterized by glomerulosclerosis and tubulointerstitial fibrosis. "Recent research using a CKD mice model showed that selective myeloid Fth1 knockout caused a reduction in renal fibrosis compared to the wild-type control, suggesting the crucial role of ferritin in controlling iron in CKD patients." (PMID 38449697, 2024).
salmonellosis (1 paper, 2024). Infections with bacteria of the genus salmonella. "Nuclear receptor co-activator 4 (NCOA4) regulates iron release via FTH1 degradation during low iron, but its role in salmonellosis is unclear." (PMID 38798412, 2024).
schizophrenia (1 paper, 2021). A major psychotic disorder characterized by abnormalities in the perception or expression of reality. "In oligodendrocytes, we observed transcriptional changes of Fth1, a ferritin gene linked to neurodegeneration, and Ngr3, a ligand to tyrosine kinase receptors that has been linked to schizophrenia." (PMID 33644903, 2021).
seminoma (1 paper, 2025). A radiosensitive malignant germ cell tumor found in the testis (especially undescended), and extragonadal sites (anterior mediastinum and pineal gland). "This study investigates the immunolabeling of key iron-related proteins (Transferrin Receptor 1, Transferrin Receptor 2, and Ferritin Heavy chain 1) and Proliferating Cell Nuclear Antigen (PCNA) in canine SCO tubules within distinct microenvironments: seminomas, Sertoli cell tumors, and isolated." (PMID 40427255, 2025).
Splenomegaly (1 paper, 2021). Abnormal increased size of the spleen. "In that study, Fth1 deletion in the myeloid lineage was associated, not only with higher bacterial loads, but also with an exacerbated inflammatory response, including larger lung lesions, splenomegaly, and loss of blood–brain barrier function." (PMID 35008695, 2021).
synovial sarcoma (1 paper, 2023). "Immunostaining of eight paraffin-embedded synovial sarcoma specimens revealed that seven specimens were positive for TFRC, and all eight specimens were positive for FTH1, suggesting abundant iron uptake and storage in synovial sarcoma cells." (PMID 37444594, 2023). "Furthermore, seven of eight synovial sarcoma clinical samples were positive for TFRC expression, and all eight were positive for FTH1 expression." (PMID 37444594, 2023). "By contrast, we did not identify a significant correlation between FTH1 expression and OS for either the full cohort (n = 39) or the subset of patients with localized synovial sarcoma (n = 26)." (PMID 37444594, 2023).
testicular tumors (1 paper, 2024). "In the DSEMs and LCTs, NCOA4 expression was considerably higher than in other canine testicular tumor types, while the expression of FTH1 appeared lower." (PMID 39272404, 2024). "In the testicular tumors, the expressions of TfR1, FTH1 and NCOA4 were altered compared to the non-neoplastic samples." (PMID 39272404, 2024).
tuberculosis (1 paper, 2023). A chronic, recurrent infection caused by the bacterium Mycobacterium tuberculosis. "Of clinical relevance, the upregulation of FTH1 in macrophages was associated with tuberculosis (TB) disease progression in humans." (PMID 37066876, 2023).
ulcerative colitis (1 paper, 2022). An inflammatory bowel disease involving the mucosal surface of the large intestine and rectum. "In this study, the expression of ferroptosis biomarker ACSL4 increased, the expression of GPX4 and FTH1 decreased, and the expression of HO-1 decreased in the PFOS group, results consistent with the study of Yeru Chen on the relationship between ferroptosis and ulcerative colitis." (PMID 36136468, 2022).
tumor (147 papers, 2012 to 2026). "Tumor-associated M2 macrophages exhibited FTH1 upregulation with concurrent NCOA4 suppression, suggesting adaptive iron sequestration as a ferroptosis resistance mechanism." (PMID 40765825, 2025). "High FTH1 expression was associated with higher macrophage infiltration, and as reported, tumor-associated macrophages can accelerate tumor growth, progression, and resistance to therapies, including immunotherapy." (PMID 38281198, 2024). "Additional qPCR analysis also revealed that high FTH1 mRNA levels were associated with advanced tumor stage and grade." (PMID 39294443, 2024). "The expression levels of ferritin subunits FTL and FTH1 were positively correlated with tumor infiltration by tumor-associated macrophages and T regulatory cells in most solid tumors, suggesting an important role in regulating tumor immunity." (PMID 37575948, 2023). "In many cancers, FTL and FTH1 levels was significantly positively correlated with tumor infiltration by tumor-associated macrophages and T regulatory cells." (PMID 33864445, 2021). "This is consistent with previously published work which has demonstrated that reduced FTH1 expression associates with increased tumor growth and progression and that reduced FTH1 or FT as a whole is prerequisites for cell transformation." (PMID 34551213, 2021). "FTH1 mRNA that encodes the heavy subunit of ferritin, was reduced in tumours compared to normal tissues with a greater reduction in the IV group, (p < 0.001)." (PMID 34211054, 2021). "FTH1 exhibited aberrant expression profiles in most solid cancers, which may cause iron metabolism disturbance to influence cancer cell proliferation and tumor microenvironment." (PMID 38281198, 2024). "Finally, TIMINER was employed to further analyze the associations between FTL and FTH1 expressions and other subtypes of tumor-infiltrating immune cells." (PMID 33864445, 2021). "Additionally, tumours with a high expression of FTH1 and IDO1 may be particularly susceptible to combination strategies involving ferroptosis inducers and immune checkpoint inhibitors, offering a potential avenue for targeted therapy." (PMID 41153383, 2025). "FTH1 is associated with iron metabolism, and may be involved in the protection of DNA from oxidative damage as well as in the regulation of inflammation and tumor immune microenvironment." (PMID 38099574, 2023). "Concurrently, intracellular tryptophan levels were found to inhibit NCOA4‐mediated selective autophagy of FTH1, stabilising FTH1 levels and promoting tumour survival." (PMID 40504108, 2026). "In vivo experiments with nude mice showed that FTH1 knockdown inhibited tumour growth, while FTH1 overexpression promoted it." (PMID 40504108, 2026). "Changes to FTH1 expression also appear to influence tumour cell proliferation and metabolism, suggesting that FTH1 is a viable therapeutic target for various diseases." (PMID 40504108, 2026). "Our findings indicate that FTH1 knockdown decelerates tumour progression, whereas FTH1 overexpression enhances tumorigenic capacity, suggesting that FTH1 facilitates malignant progression in HCC cells." (PMID 40504108, 2026). "Analysis of 30 fresh HCC and adjacent non‐cancerous tissues revealed significant FTH1 mRNA upregulation in the tumour samples." (PMID 40504108, 2026). "The combination treatment of JQ1 and FTH1 silencing suggests a potential anti‐tumor strategy to overcome chemotherapy resistance in aggressive NSCLC." (PMID 40652527, 2025). "Secondly, the M2-polarized macrophages are mainly composed of M2-like tumor-associated macrophages (TAMs) with tumor-promoting characteristics (CD163, FTH1, FTL, TIMP1), and there is a polarization from M1 to M2." (PMID 40948800, 2025). "In K562 tumor cells, however, hypoxia only slightly activated FTH1 translation by reducing IRE-IRP interactions." (PMID 39852175, 2025).